CCNA2 (cyclin A2)
Diseases named in the same sentence as CCNA2 in open-access papers (continued):
Sharing a sentence is not in itself a finding about the gene and the disease.
tumor (continued). "Therefore, we analyzed the correlation between tumor mutation burden and the expression of targets, and the results showed that the expression of AURKA, CCNA2, CCNE1, CDK1, CHEK1, and PLK1 were significantly positively correlated with the tumor mutation burden." (PMID 36483630, 2022). "Interestingly, we also found that CCNA2 and H2AFX have significantly higher level of expression in fast-growing tumors compared to slow-growing tumors, indicating their association with rapid tumor growth." (PMID 34659334, 2021). "We observed that OSCC patients with high expression of cyclin A2 in their cell tumours presented a significantly lower 5-year overall survival even in multivariate survival analyses, indicating that cyclin A2 expression could be an independent prognostic marker in OSCC." (PMID 29785357, 2018). "Therefore data from clinical HNSCC patients also demonstrate that PTHLH might regulate tumor growth through cell cycle regulators, namely, CCNA2, CCNE2, and CDC25A." (PMID 28120940, 2017). "The expression of Ccna2, Ccnb2, and Cdk1 were low, which could reduce G1/S-phase arrest and the transition from G2 to M phase, furthermore enhanced the ability of anti-apoptosis of tumor stem cells." (PMID 28163656, 2017). "We also detected the expression of CCNA2 and HMGA2 by IHC stating assay in CDX and PDX model tumor tissues and found that the knockdown of 6PGD decreased the expression of CCNA2 and HMGA2 proteins." (PMID 40611205, 2025). "For instance, in the comparison between PCa tumor and normal samples, DiCE identified 61 cancer fitness genes, including MYC, CCNA2, PLK1, PTTG1, EPCAM, and MTOR, that were overlooked by typical DEA but are well-documented contributors to PCa progression." (PMID 40626556, 2025). "It regulates cyclin A2 and cyclin B expression, key drivers of G2/M transition, and its knockdown disrupts cyclin-CDK activity, inhibiting tumor cell proliferation." (PMID 40396172, 2025). "Western blot analysis substantiated these findings at the protein level, revealing significantly elevated expression of CCNA2, CSRP2, ILF2, KIF2C, RACGAP1, and VARS in HCC tissues versus adjacent non-tumor tissues." (PMID 41323394, 2025). "The analysis revealed that the five key genes, including BUB1, BUB1B, CDK1, UBE2C, and CCNA2, exhibited higher expression in LUAD tumor tissues compared to normal tissues in all cases." (PMID 41181148, 2025). "Western blotting revealed significantly elevated levels of CCNA2, CSRP2, ILF2, KIF2C, RACGAP1, and VARS proteins in HCC tissues compared to adjacent non-tumor tissues." (PMID 41323394, 2025). "This study found that in cancer types with over 12 tumor and para-cancer tissues, the genes RRM2, TK1, CCNB1, DLGAP5, CCNA2, MYBL2, and HJURP were repeatedly overexpressed across various cancer tissues." (PMID 39669580, 2024). "HMGB2 in POSTN+ fibroblasts is predicted to bind to PLD2, LRP5, MYLK, and CD44 on tumor cells, regulating downstream genes, including BIRC5, CCNA2, CCNB1, CCNB2, CDC20, and MKI67, which are related to the cell cycle." (PMID 38519500, 2024). "The expression of four genes (TOP2A, CDK1, CCNA2, and CCNB2) with high scores in module 1 were more in tumor samples and have been identified by GEPIA analysis." (PMID 38895552, 2024). "Overall, we found that NPM3 was positively associated with genes that promote tumor proliferation, with NPM3 positively regulating the expression of CCNA2 and MAD2L1, and NPM3 was negatively correlated with the tumor suppressor RASSF5." (PMID 37254219, 2023). "As expected, AURKB, CCNA2, and PLK1 were upregulated in the tumor cell line compared to that in normal gastric epithelial cells." (PMID 37238607, 2023).
tumor (continued). "The CDK1, CDK5, CDC20, CCNA2, CCNB1 and CCNB2 expression levels (tumor sample: n = 369 vs. normal sample: n = 160) were upregulated in HCC group compared with the non-carcinoma group (Analysis by GEPIA dataset)." (PMID 36605491, 2023). "The result also showed that CDK1, CDK5, CDC20, CCNA2, CCNB1 and CCNB2 mRNA expression levels within tumor tissues were significantly increased compared with the adjacent normal tissues." (PMID 36605491, 2023). "In addition, we found that the expressions of AURKA, CCNA2, CCNE1, CDK1, CHEK1, and PLK1 were all positively correlated with TMB, which was consistent with previous research results, and there was a positive correlation between tumor dryness and tumor mutation burden." (PMID 36483630, 2022). "CDK1, AURKB, CCNA2, and CHEK1 were highly expressed in immune cells, suggesting that histone phosphorylation is closely related to the tumor immune environment." (PMID 36120466, 2022). "Cell cycle-related genes such as AURKA, AURKB, GTSE1, CCNA2, and MYBL2 were shown to promote tumor progression of LUAD." (PMID 36304306, 2022). "Next, we confirmed the positive linear correlations between the mRNA expression of MKI67 vs. CCNA2, CCNB1, CCNB2, and CCNE2, suggesting their role in tumor progression." (PMID 36151566, 2022). "In terms of immune microenvironment, we found that the expressions of AURKA, CCNA2, CCNE1, CDK1, CHEK1, and PLK1 were negatively correlated with tumor immune infiltrating cells." (PMID 36483630, 2022). "We then examined the expression of 9 model genes in single cells and found that CDK1, AURKB, CCNA2, and CHEK1 are mainly expressed in CD4 cells, while PRKAA2, CDK5, and PRKCD are mainly expressed in tumor cells." (PMID 36120466, 2022). "Immunohistochemistry was further used to detect the tumor tissue stripped from nude mice with anti-CDCA7, anti-CCNA2, and anti-Ki-67 antibodies." (PMID 34737951, 2021). "A clear common up-activation pattern is observed in tumor samples of three cancer types, but only LEPR and CCNA2 nodes are differentially expressed in the same direction in all three cancers." (PMID 34039407, 2021). "Compared with the NC tumours, the protein level of CD11b and CD14 greatly increased in ZEB1 knock‐down tumours, while the expression of cyclin D1, cyclin A2, p‐Rb and CDK4 was markedly decreased in ZEB1 knock‐down tumours." (PMID 33960640, 2021). "Exosomes containing circRNAs secreted by adipocytes promote tumor growth and reduce DNA damage by inhibiting miR-34a and activating USP7/cyclin A2 signaling pathway." (PMID 34031263, 2021). "Our previous research screened four genes from ENZ-resistant C4-2B cells, which were CCNA2, CKAP2L, NCAPG, and NUSAP1, and confirmed that the protein levels of these four genes also remained higher in ENZ-resistant xenograft tumor tissues." (PMID 34746227, 2021). "The expression of CCNA2 and CCNB1 was also positively correlated with tumor-killing immune cells, such as CD8+ T cells." (PMID 33996604, 2021). "Meanwhile, the expression of CCNA2 and CCNB1 was positively correlated with tumor-killing immune cells, such as CD8+ T cells.The copy numbers of CCNA2, CCNB1, CCND1, CCNE1, and CCNF was positively related to gene expression." (PMID 33996604, 2021). "Western blotting showed that E2F4 knockdown promoted the expression of CD11b and CD14 and inhibited the expression of cyclin D1, cyclin A2, P‐Rb and CDK4 compared with the expression in control tumours." (PMID 31943751, 2020). "CCNA2 also facilitates EMT via the integrin αvβ3 signaling, representing a crucial regulator of tumor cells metastasis." (PMID 33665162, 2020). "Six weeks post-injection, tumor volume increased, and MAGE-A3 and cyclin A2, B1 and E1 protein levels were elevated in syngeneic tumors compared to normal murine keratinocytes and Pam 212 cells grown in vitro." (PMID 33227008, 2020).
tumor (continued). "Next, we further identified 21 anti-tumor drugs (e.g., Cladribine, Gallium nitrate, Dinaciclib, Alvocidib, Suramin) targeting RRM2, CDK1 and CCNA2." (PMID 33083112, 2020). "In accordance with our above results, Western blot analysis revealed that CCNA2, MCM7 and SKP2 expression were decreased in the MTHFD2 knockdown tumour tissues compared with shCtrl tumour tissues." (PMID 31778025, 2020). "And the exosome circRNAs, secreted from liver adipocytes, promoted tumor growth by controlling miR-34a level and activating the USP7/CCNA2 signaling pathway." (PMID 31886176, 2019). "With ‘TF regulation’ checked, TF-TG correlation coefficients are provided and then user can get the TFs targeting CCNA1, CCNA2 and see that the correlation coefficient between FOXP3 and CCNA2 is much different in normal samples (0.58) and tumor samples (0.16)." (PMID 29504910, 2018). "Bcl2, VEGFA, PTEN, Jun, Fos, APC2 were up-regulated and Ccna2, Cdc25a, Mcm3, Mcm6, Ccnb2, Mcm5, Cdk1, Gadd45a, Myc were down-regulated in MMQ tumor stem-like cells group." (PMID 28163656, 2017). "In pathway in cancer and cell cycle, Bcl2, VEGFA, PTEN, Jun, Fos, APC2 were up-regulated and Ccna2, Cdc25a, Mcm3, Mcm6, Ccnb2, Mcm5, Cdk1, Gadd45a, Myc were down-regulated in the MMQ tumor stem-like cells." (PMID 28163656, 2017). "In the pathway in cell cycle, we found that the expression of Ccna2, Cdc25a, Mcm3, Mcm6, Ccnb2, Mcm5, Cdk1, Gadd45a were down-regulated in the MMQ tumor stem-like cells." (PMID 28163656, 2017). "Together, the repression of FXR and miR-22, along with the high expression of CCNA2, were apparently observed in HCC tumor tissues, either of which demonstrated high correlation with the other." (PMID 27738335, 2016). "Consistent with a proposed switch in the AR driven transcriptional program with local tumour progression, we observed a consistent increase in the expression of a number of these genes in higher-grade tumours, particularly CDK1, UBE2C, CDC20 and CCNA2." (PMID 27120785, 2016). "The protein levels of Cyclin E1, Cyclin D3, Cyclin D1,Cyclin A2, CDK2 and CDK4 were significantly decreased in tumor tissues harvested from miR-188 injected mice." (PMID 25304455, 2014). "Unsupervised hierarchical cluster based on relative quantification of the 5 E2F-induced genes, CCNA2, CCNB1, CCNB2, MSH6 and MCM7, by RT–qPCR divided the 24 tumours into two groups." (PMID 22045185, 2011). "Consistent with the immunohistochemistry in other studies, several cell cycle regulators (e.g., CDKN2A (p16), CCNA2, CCNB1, CCNE2) were expressed at significantly higher levels in the tumor epithelium of African-Americans than European-Americans." (PMID 19225562, 2009). "In CPTAC-OTSCC samples (n=18), CCNA2 protein expression was significantly higher in tumor tissues than in non-tumoral tissues (p <0.0001), with a positive correlation between mRNA and protein levels (r=0.56, p=0.01)." (PMID 41779475, 2026). "According to the tumorigenicity assay for the nude mice in this study, the knockdown of CCNA2 could significantly inhibit the growth and proliferation of tumor xenografts, and it also could inhibit the EMT-signaling pathway in tumor xenografts." (PMID 40345591, 2025). "Furthermore, CCNA2 presented a significant high expression trend in ccRCC tumor than in normal tissues and Pearson's r showed that TAF7 expression was positively correlated with CCNA2 expression." (PMID 38904013, 2024). "Moreover, elevated CCNA1 and CCNA2 expression levels activates the PI3K/AKT pathway, promoting tumor growth and cell survival." (PMID 38384287, 2024). "Moreover, integration into the TERT, CCNA2, CCNE1, and KMT2B genes is more common in the HCC group than in the non-tumor group infected with HBV." (PMID 36992198, 2023). "Moreover, the expression levels of BUB1, BUB1B, CDK1, CCNA2, MCM10 were significantly higher in CRC tumor tissues compared with normal tissues based on the GEPIA database." (PMID 37466419, 2023).
tumor (continued). "Currently, it has been confirmed that cyclin A2 is highly expressed in multiple tumor tissues, while it is not expressed or low expressed in normal tissues." (PMID 35929837, 2022). "Cyclin A2 (CCNA2) regulates the cell cycle and contributes to tumor growth." (PMID 36389792, 2022). "Indeed, the present study showed that CCNA2, CEP55, KIF11, KIF4A, and ZWINT were the top five genes that were significantly and positively correlated with CDK1 in all tumor types from the TCGA database." (PMID 35681641, 2022). "In addition, CCNE1, CCNE2, CCNB2, CCNA2, and CDK1 genes were highly expressed in fetal tumor tissues." (PMID 34395530, 2021). "Collectively, CCNA2, CDK1, and CDC20 may serve as promising biomarkers for HB and provide prospects for designing targeted therapies using synthetic inhibitors as anti-tumor agents." (PMID 33718368, 2021). "In this study, the differential expression analysis showed that among all cyclin family members, there were six significant DEGs (CCNA2, CCNB1, CCND1, CCNE1, CCNF, and CCNJL), five of which were overexpressed in tumor samples compared to normal controls, while CCNJL was downregulated." (PMID 33996604, 2021). "CCNA2, CCNB1, and CCNE1 were co-expressed with BIRC5, a well-known cancer therapeutic target which directly regulates both apoptosis and mitosis in cancer cells during tumorigenesis and tumor metastasis." (PMID 33996604, 2021). "In addition, differential analysis from the ONCOMINE online database of tumor and normal tissue in two cohorts indicated that ZWINT, PRC1, CDKN3, CDK1 and CCNA2 were highly expressed in ACC samples." (PMID 31572440, 2019). "In addition, PDAC patients with neoplasms of histologic grade G3-4 had significantly higher BUB1B, CCNA2, and CDC20 levels than those with grade G1-2 neoplasms (all P<0.05), and high levels of BUB1B and CDC20 contributed to tumor formation (both P<0.05)." (PMID 30765611, 2019). "In addition, PDAC patients with neoplasms of histologic grade G3-4 had significantly higher BUB1B, CCNA2 and CDC20 levels (all P<0.05)." (PMID 30765611, 2019). "Although we could not identify the responsible genes that promoted transcription of CCNA1 and CCNA2, we found that positive correlation between FOXP3 as TF and CCNA2 as TG is disrupted in tumor samples." (PMID 29504910, 2018). "MP-HX downregulated the expression of genes that could promote anti-apoptotic effect, cell cycle progression, tumor development and progression, which include BIRC5, CCNA2, CCNB1, CCNB2, CCNE2, CDK1/2/6, GINS2, HELLS, MCM2/10 PLK1, RRM2 and SKP2." (PMID 30042885, 2018). "We found that CCNA2, CCNE2 and CDC25A are significantly up-regulated in PTHLH expression Ca9-22 cells and those are also up-regulated in the in Taiwanese (p < 0.01) and TCGA data (p < 0.001) HNSCC tumor." (PMID 28120940, 2017). "In addition, cell cycle markers, for instance, cyclin A2, Cyclin Dependent Kinase-2, 6 and MAPK1, 14, 10 promote the tumour progression whereas caspase 3 inhibits the tumour progression." (PMID 26385094, 2015). "Cyclin A2 expression was found to be at intermediatelevel in the tumor tissues from vehicle treated mice whereas in the tumortissues from SQDG treated mice cyclin A2 expression increased to the high levels,suggesting S phase arrest in the SQDG treated tumor cells." (PMID 26189912, 2015). "Furthermore, SW480-derived microvesicles are enriched with CENPE, KIF15, CEP55, CCNA2, NEK2, PBK, and CDK8 that are M-phase-related transcripts involved in tumorigenesis and tumor progression." (PMID 19930720, 2009). "Identification of Core Targets: Five critical anti-GC targets (CDK1, CCNA2, TOP2A, CHEK1, and PLK1) were identified, with a focus on their roles in cell cycle regulation and chemotherapy resistance, providing mechanistic insights into Diosgenin’s anti-tumor effects." (PMID 40487391, 2025).
tumor (continued). "It has been demonstrated that HuR binds to the 3′ UTR of cyclin A2 and stabilize the mRNA of cyclin A2 in CRC cells in a cell cycle-dependent manner, as cyclin A2, a cofactor of cyclin dependent kinase 2 (CDK-2) enhances tumor cells progression through the S phase." (PMID 38801618, 2024). "The results revealed the high expression of AURKB, CCNA2, and PLK1 in tumor tissues when compared to normal tissues and we also found that there was a strong positive correlation with the DNA replication, G2M checkpoint, and tumor proliferation signature pathways." (PMID 37238607, 2023). "As HOXD9 is an important transcription factor promoting tumor proliferation, we examined the correlation between HOXD9 mRNA levels and proliferation markers PCNA, Ki-67 as well as cell cycle related genes CCNA2 and CCNB1 to validate whether HOXD9 can facilitate ATC proliferation." (PMID 37974228, 2023). "Besides, studies have confirmed that Cyclin A2 is highly expressed in multiple tumor tissues, but not or lowly expressed in normal tissues." (PMID 37100467, 2023). "However, there is still no pan-cancer evidence for CCNA2 in various tumor types based on large clinical data." (PMID 35480884, 2022). "Among them, the enrichment of HBV-DNA integration in TERT, CCNE1, and CCNA2 genes in tumoral samples has also been confirmed by analyzing the publicly available database VISDB, collecting 20558 HBV-DNA integration sites in tumor/peritumor/non-tumor liver samples from 45 publications." (PMID 36118192, 2022). "CCNA2 could activate CDK2 during the S phase, allowing the cell cycle to proceed normally, and it also could be recognized by high-avidity T-cells to perform function in tumor immunity." (PMID 36325324, 2022). "Therefore, increased CCNA2 promotes the proliferation of ESCC cells, thus promoting tumor growth." (PMID 34737951, 2021). "Thus, EA preserved Ccna2 expression and hematopoietic cell proliferation in the BM without enhancing tumor proliferation." (PMID 34552585, 2021). "However, CCNA2 knockdown did not change MRE11A protein levels in neither NCI-H520 nor in OVCAR-3 tumor cells." (PMID 32076484, 2020). "Of the 134 cores of the cyclin A2 slides, 13 (9.70%) cores could not be analysed: 8 (5.97%) cores contained no tumour cells, 4 (2.99%) were lost, and 1 (0.75%) had not sufficient cells for scoring." (PMID 29785357, 2018). "Il6 deficiency also reduced hepatic mRNA levels of Stat3 target genes (Birc5, Bcl2l1 and Ccnd1), cyclins (Ccna2, Ccnb1, Ccnb2), and markers of proliferation (Mki67) and HCC (Afp) in livers from FGF19-expressing mice, further demonstrating the role of IL-6 in mediating FGF19-driven tumour growth." (PMID 28508871, 2017). "Additionally, we investigated the expressions of FXR, miR-22 and CCNA2 in tumor samples and non-tumorous tissues of HCC from available database and validated these three targets in another set of HCC." (PMID 27738335, 2016). "Furthermore, miR-22 suppresses tumor proliferation, tumorigenesis, and metastasis by targeting proteins, including Protein Kinase C Inhibitor Protein-1 YWHAZ, cluster of differentiation 147 (CD147), galectin-1 (LGALS1), cyclin A2 (CCNA2), and specificity protein 1 (SP1)." (PMID 39953622, 2025). "Based on the EPIC algorithm, CCNA2 and CDK2 expression levels in SARC were negatively correlated with the infiltration level of CD4+ T cells (cor = −0.194, P = 2.62e−03), implying that our dimers also could target CCNA2 and CDK2 to affect the tumor immunity in MG-63 cells." (PMID 36325324, 2022). "The results indicated that CDCA7 gene might act as a tumor promoter in ESCC and its copy number amplification or increased expression may accelerate the cell cycle process and promote cell proliferation by binding to the genome of CCNA2 functional domain and increasing its expression in ESCC." (PMID 34737951, 2021).